ASCC3 (activating signal cointegrator 1 complex subunit 3)
Description:
ATPase involved both in DNA repair and rescue of stalled ribosomes. 3'-5' DNA helicase involved in repair of alkylated DNA: promotes DNA unwinding to generate single-stranded substrate needed for ALKBH3, enabling ALKBH3 to process alkylated N3-methylcytosine (3mC) within double-stranded regions. Also involved in activation of the ribosome quality control (RQC) pathway, a pathway that degrades nascent peptide chains during problematic translation. Drives the splitting of stalled ribosomes that are ubiquitinated in a ZNF598-dependent manner, as part of the ribosome quality control trigger (RQT) complex. Part of the ASC-1 complex that enhances NF-kappa-B, SRF and AP1 transactivation.
Synonyms: ASC1p200; HELIC1; RNAH; dJ121G13.4; dJ467N11.1; MRT81
Tractability: PROTAC: ubiquitination databases record sites on it; its protein half-life has been measured.
Gene: Protein-coding gene on chromosome 6 (100,508,194 to 100,881,407, reverse strand). Ensembl gene ENSG00000112249.
Subcellular location: Nucleus; Nucleus speckle; Cytoplasm, cytosol
Subcellular location (Human Protein Atlas): Cytosol; Golgi apparatus
Pathways (Reactome):
DNA Repair: ALKBH3 mediated reversal of alkylation damage
Metabolism of proteins: ZNF598 and the Ribosome-associated Quality Trigger (RQT) complex dissociate a ribosome stalled on a no-go mRNA
Gene Ontology:
Molecular function: 3'-5' DNA helicase activity; ATP hydrolysis activity; protein binding; RNA binding; ATP binding; helicase activity; nucleic acid binding
Biological process: DNA alkylation repair; rescue of stalled ribosome; ribosome disassembly; ribosome-associated ubiquitin-dependent protein catabolic process; DNA replication
Cellular component: cytosol; cytosolic ribosome; DNA repair complex; membrane; nuclear speck; nucleus; RQC-trigger complex; nucleoplasm
Genetic constraint (gnomAD): Loss-of-function variants: 145 observed, 245.87 expected, observed/expected ratio (o/e) 0.59, 90% interval 0.51 to 0.68. The upper end of that interval is the gene's LOEUF score, 0.68, which puts it in group 2 of 6, group 1 being the genes least tolerant of losing a copy. Missense variants: 2,178 observed, 2,650.1 expected, observed/expected ratio (o/e) 0.82, 90% interval 0.79 to 0.85. Synonymous variants: 912 observed, 902.88 expected, observed/expected ratio (o/e) 1.01, 90% interval 0.96 to 1.07.
Homologues: Orthologues: chimpanzee ASCC3 (99% identical), macaque ASCC3 (99% identical), rabbit ASCC3 (94% identical), guinea pig ASCC3 (93% identical), dog ASCC3 (92% identical), mouse Ascc3 (92% identical), pig ASCC3 (92% identical), tropical clawed frog ascc3 (79% identical), zebrafish ascc3 (67% identical), Drosophila melanogaster obe (50% identical), Caenorhabditis elegans Y54E2A.4 (43% identical), rat Ascc3 (27% identical). Paralogues in human: SNRNP200 (39% identical), HFM1 (16% identical), POLQ (13% identical), DDX60 (9% identical), DDX60L (8% identical), SKIC2 (8% identical), HELQ (7% identical), MTREX (7% identical).
Diseases named in the same sentence as ASCC3 in open-access papers:
ASCC3 is named in the same sentence as 28 diseases in open-access papers, as found by Europe PMC text mining. Sharing a sentence is not in itself a finding about the gene and the disease. The quoted sentences say what the papers report.
prostate carcinoma (4 papers, 2017 to 2024). A carcinoma that arises from epithelial cells of the prostate gland. "Recently, it was elegantly shown that ALKBH3 is associated with the helicase ASCC3 to demethylate endogenously methylated 3-meC in ssDNA in prostate cancer cells." (PMID 28205560, 2017). "Next, SNVs in DNA repair genes (RAD51-associated protein 1 [RAD51 AP1], structural maintenance of chromosomes 1A [SMC1A], and activating signal cointegrator 1 complex subunit 3 [ASCC3]) were observed only in the RR prostate cancer cells." (PMID 39719436, 2024). "In parental PC-3 prostate cancer cells, a similar staining pattern of ASCC3 and ALKBH3 was observed as in HeLa, except that more distinct cytoplasmic P-bodies were present in the untreated PC-3 cells." (PMID 34217309, 2021). "A role of ASCC3 in cancer development or progression is also suggested by the observation that knockdown of ASCC3 in a prostate cancer cell line suppresses cell proliferation." (PMID 33139697, 2020).
developmental delays (3 papers, 2021 to 2025). "In conclusion, this study presents the first report of three patients with ASCC3 variations associated with developmental delay and muscle fatigue in Chinese children." (PMID 39286456, 2024). "These eleven individuals from seven unrelated families all have biallelic variants in ASCC3 and a variable neurobehavioral and neuromuscular phenotype All ten of the post-natal individuals had some reported developmental delays, and 5/10 had significant hypotonia." (PMID 35047834, 2021). "ASCC3 is involved in the regulation of signal transducer and activator of transcription 3 (STAT3) and interferon response genes, and variants are associated with developmental delays and increased pTau." (PMID 40386807, 2025). "Based on these individuals, we suggest that when a clinician encounters a cluster of symptoms including global developmental delay, hypotonia, and/or fatigue, but without other major anomalies, then biallelic variants in ASCC3 should be considered." (PMID 35047834, 2021).
Anxiety (2 papers, 2022 to 2025). Intense feelings of nervousness, tension, or panic often arise in response to interpersonal stresses. "In the present study, we show that Ascc3−/− mice are lethal, and Ascc3Camk2amutants showed hyperactive behaviour and increased rearing in the actimetric cages, and reduced anxiety-related behaviour in the elevated plus maze." (PMID 36551904, 2022). "Some gene-trait overlaps showed compelling biological convergence, such as ASCC3, which was associated in dogs with non-social fear, and in humans with neuroticism, anxiety, sensitivity or hurt feelings, and multiple other related traits." (PMID 41284867, 2025).
Intellectual disability (2 papers, 2021 to 2024). "ASCC3 (Activating Signal Cointegrator 1 Complex, Subunit 3) was initially identified as a gene associated with intellectual disability (ID) and cognitive impairment by Najmabadi H (MIM: 620700)." (PMID 39286456, 2024). "Whole-exome sequencing of three children with intellectual disability in our hospital identified compound heterozygous variants related ASCC3 gene." (PMID 39286456, 2024). "They found that homozygous variants in ASCC3 were linked to intellectual disability in four individuals from one family, and the phenotype segregated separately from unaffected members." (PMID 39286456, 2024). "This study centers on intellectual disability gene discovery, and they briefly report four family members with homozygous missense ASCC3 variants identified by exome sequencing that segregate with the phenotype." (PMID 35047834, 2021). "This study present the first report of Chinese children carrying compound heterozygous genetic variants in ASCC3 with LOF variants, elucidating the relationship between these variants and various aspects of intellectual disability." (PMID 39286456, 2024).
lung cancer (2 papers, 2025). A malignant neoplasm involving the lung. "It was reported that ASCC3 could collaborate with ALKBH3 to repair DNA alkylation damage in prostate and lung cancer cells that sustained high levels of ALKBH3 expression." (PMID 40067902, 2025).
viral infection (2 papers, 2021 to 2022). "Intriguingly, however, we were unable to detect increased expression of IFN itself, in line with work on ASCC3 deficiency from the Diamond laboratory, which nevertheless showed that the response generated was sufficient to elicit protection against virus infection." (PMID 34111399, 2021). "Silencing of ASCC3 resulted in upregulation of multiple antiviral ISGs and attenuation of viral infection, whereas ectopic expression of ASCC3 resulted in downregulation of ISGs and increased viral infection." (PMID 36187485, 2022). "Crucially, it has previously been shown that ASCC3 or ZNF598 deficiency induces not only ISG expression but also a broad antiviral state: in the absence of these RQC factors, cells activate the inflammatory response to an extent that is sufficient to inhibit virus infection." (PMID 34111399, 2021). "Since ZNF598 and ASCC3 are both early RQC factors that sense ribosome collisions, future studies will test whether handling of ribosome collision is a common mechanism by which ZNF598 and ASCC3 negatively regulate ISG expression and antiviral response in various viral infection conditions." (PMID 36187485, 2022).
cervical cancer (1 paper, 2025). A primary or metastatic malignant neoplasm involving the cervix. "In our pan-cancer prognostic study, we found that high ASCC3 expression serves as a protective factor for patients with clear cell renal carcinoma, while it acts as a risk factor for cervical cancer patients." (PMID 40881169, 2025).
cervical squamous cell carcinoma (1 paper, 2025). A squamous cell carcinoma arising from the cervical epithelium. "The results showed that high ASCC3 expression was a protective factor for patients with kidney renal clear cell carcinoma (KIRC), while it was a risk factor for patients with cervical squamous cell carcinoma and endocervical adenocarcinoma (CESC)." (PMID 40881169, 2025).
cholangiocarcinoma (1 paper, 2025). A carcinoma that arises from the intrahepatic biliary tree (intrahepatic cholangiocarcinoma) or from the junction, or adjacent to the junction, of the right and left hepatic ducts (hilar cholangiocarcinoma). "The results indicated that ASCC3 expression had no impact on the OS of patients with esophageal carcinoma (ESCA), stomach adenocarcinoma (STAD), colon adenocarcinoma (COAD), liver hepatocellular carcinoma (LIHC), cholangiocarcinoma (CHOL) and pancreatic adenocarcinoma (PAAD)." (PMID 40881169, 2025).
rectal adenocarcinoma (1 paper, 2025). "Additionally, we explored the regulatory mechanisms of ASCC3 and its association with tumor immunity in rectal adenocarcinoma using TIMER, IMMPORT, DAVID databases, and CIBERSORT analysis." (PMID 40881169, 2025). "ASCC3 is highly expressed in various cancer types, including rectal adenocarcinoma, which is highlighted with a red box." (PMID 40881169, 2025). "Our study reveals that ASCC3 expression is elevated in various cancers, including rectal adenocarcinoma, compared to normal tissues, suggesting its amplificatory role in cancer." (PMID 40881169, 2025). "Our study shows that multiple immune genes associated with ASCC3, including JAK1, NFKB1, SEMA5A, NR2C2, CNTF and CREB1, positively impact the prognosis of rectal adenocarcinoma patients." (PMID 40881169, 2025). "We utilized data from The Cancer Genome Atlas (TCGA) and GEO to investigate the prognostic value of the four subunits, with a focus on ASCC3, in pan-cancers including rectal adenocarcinoma." (PMID 40881169, 2025). "This suggests that ASCC3 may mediate antitumor immune responses by coordinating the functions of various immune cells, thereby exerting a protective effect in rectal adenocarcinoma patients." (PMID 40881169, 2025). "This study demonstrates that high expression of ASCC3 can protect rectal adenocarcinoma patients by maintaining genomic stability through its DNA damage repair function, as well as by participating in the regulation of the cell cycle, proliferation, and differentiation." (PMID 40881169, 2025). "ASCC3 is a specific protective factor for rectal adenocarcinoma across various cancer types, particularly in digestive system cancers, and can synergize with several immune-related genes, including JAK1, NFKB1, SEMA5A, NR2C2, CNTF, and CREB1, to influence patient prognosis." (PMID 40881169, 2025). "However, the exact role of ASCC3 in digestive system cancers, particularly in rectal adenocarcinoma, remains unclear." (PMID 40881169, 2025). "However, the exact role of ASCC3 in digestive system cancers, particularly in rectal adenocarcinoma (READ), remains unclear." (PMID 40881169, 2025). "Next, we analyzed the expression levels of ASCC3, ASCC1, ASCC2, and TRIP4 in TCGA rectal adenocarcinoma samples." (PMID 40881169, 2025).
rectal cancer (1 paper, 2025). A primary or metastatic malignant neoplasm that affects the rectum. "Subgroup analysis of the rectal cancer cohort suggests that high ASCC3 expression is associated with better prognosis, particularly in late-stage, non-metastatic patients, especially among females." (PMID 40881169, 2025). "We found that high expression of ASCC3 in rectal cancer patients is associated with better prognosis." (PMID 40881169, 2025). "Our mutational analysis of ASCC3 across various cancers suggests that ASCC3 mutation frequency is relatively low in rectal cancer." (PMID 40881169, 2025). "Therefore, ASCC3 retains considerable diagnostic and prognostic value, with significant implications for future research in rectal cancer." (PMID 40881169, 2025). "We also assessed the association of ASCC3 expression with these functional states in multiple digestive system cancers, and the results showed that ASCC3 exhibited a stronger correlation with these states in rectal cancer compared to other digestive system cancers." (PMID 40881169, 2025). "ASCC3 can serve as an independent prognostic factor for rectal cancer patients, particularly in younger individuals." (PMID 40881169, 2025). "This study elucidates the protective role of high expression of ASCC3 in rectal cancer patients, suggesting its potential as a prognostic biomarker for rectal cancer." (PMID 40881169, 2025). "Univariate regression revealed that age >65 years, N1 & N2 stage, M1 stage and Stage III & IV were unfavorable prognostic factors (HR > 1), whereas high ASCC3 expression was a protective factor for rectal cancer prognosis (HR < 1)." (PMID 40881169, 2025). "Our findings indicate that rectal cancer patients with high ASCC3 expression tend to have a better prognosis compared to those with other digestive system cancers." (PMID 40881169, 2025). "To further investigate the mechanism of ASCC3 in the tumor immune microenvironment of rectal cancer, we first analyzed the relationship between ASCC3 and six common immune cell types in rectal cancer using the TIMER database." (PMID 40881169, 2025). "Since ASCC3 has been identified as a protective factor for rectal cancer in this study, a smaller area under the curve (AUC), closer to 0, indicates better prognostic diagnostic efficacy." (PMID 40881169, 2025). "The results indicate that among the 166 rectal cancer patient samples from the TCGA dataset, patients with high ASCC3 expression had significantly better survival rates (Log-rank test: p = 0.012; Cox regression test: HR = 0.36 (0.16–0.83), p = 0.016)." (PMID 40881169, 2025). "The results indicate that high ASCC3 expression is a favorable prognostic factor for patients, and ASCC3 can serve as an independent prognostic factor for rectal cancer patients." (PMID 40881169, 2025). "The positive correlation between ASCC3 and DNA damage and repair in rectal cancer, as well as its activation of the cell cycle and inhibition of the EMT pathway, further supports this notion." (PMID 40881169, 2025). "ASCC3 can serve as a prognostic biomarker for rectal cancer." (PMID 40881169, 2025). "Therefore, this study employs multi-omics analysis and machine learning to thoroughly investigate the prognostic potential and mechanisms of ASCC3 in rectal cancer." (PMID 40881169, 2025). "We hypothesize that ASCC3 exerts its protective effect on rectal cancer patients by regulating the functions of these six immune-related genes." (PMID 40881169, 2025). "Moreover, high expression of ASCC3 in rectal cancer can protect patients through its unique DNA damage repair functions and by synergizing with various immune-related genes." (PMID 40881169, 2025). "Therefore, we infer that high ASCC3 expression may be a protective factor for rectal cancer patients." (PMID 40881169, 2025). "Therefore, we hypothesize that ASCC3 may exert a specific protective effect in rectal cancer by modulating stronger cell cycle regulation, DNA damage and DNA repair." (PMID 40881169, 2025).
rectal cancer (continued). "The combination of ASCC3 with several immune-related genes, including JAK1, NFKB1, SEMA5A, NR2C2, CNTF and CREB1, plays a significant predictive role in the prognosis of rectal cancer patients." (PMID 40881169, 2025). "Additionally, our diagnostic and prognostic models, constructed using machine learning, highlight the significant predictive value of ASCC3 in combination with various immune-related genes, including JAK1, NFKB1, SEMA5A, NR2C2, CNTF and CREB1, for rectal cancer prognosis." (PMID 40881169, 2025). "Furthermore, although this study reveals the protective role of ASCC3 in rectal cancer patients, it does not explore how ASCC3 influences the tumor immune microenvironment by regulating immune-related genes and T cell immune functions." (PMID 40881169, 2025).